TMSB10 (thymosin beta 10)
Description:
Plays an important role in the organization of the cytoskeleton. Binds to and sequesters actin monomers (G actin) and therefore inhibits actin polymerization (By similarity).
Synonyms: TB10; MIG12
Tractability: PROTAC: ubiquitination databases record sites on it; its protein half-life has been measured.
Gene: Protein-coding gene on chromosome 2 (84,904,923 to 84,906,680, forward strand). Ensembl gene ENSG00000034510.
Subcellular location: Cytoplasm, cytoskeleton
Gene Ontology:
Molecular function: protein binding; actin monomer binding; protein sequestering activity
Biological process: regulation of cell migration; actin filament organization
Cellular component: cytoskeleton
Genetic constraint (gnomAD): Loss-of-function variants: 4 observed, 3.17 expected, observed/expected ratio (o/e) 1.26, 90% interval 0.57 to 1.9. That is too few expected variants to judge how well the gene tolerates losing a copy. Missense variants: 44 observed, 56.6 expected, observed/expected ratio (o/e) 0.78, 90% interval 0.61 to 1. Synonymous variants: 17 observed, 21.68 expected, observed/expected ratio (o/e) 0.78, 90% interval 0.54 to 1.18.
Homologues: Orthologues: chimpanzee TMSB10 (100% identical), dog TMSB10 (100% identical), macaque TMSB10 (100% identical), mouse Tmsb10b (100% identical), rabbit TMSB10 (100% identical).
Diseases named in the same sentence as TMSB10 in open-access papers:
TMSB10 is named in the same sentence as 78 diseases in open-access papers, as found by Europe PMC text mining. Sharing a sentence is not in itself a finding about the gene and the disease. The quoted sentences say what the papers report.
breast carcinoma (10 papers, 1996 to 2026). "We next explored the specific mechanism underlying the pro-proliferative role of TMSB10 in breast cancer cells." (PMID 28179017, 2017). "On analysis of the TCGA breast cancer datasets, TMSB10 was positively associated with the T308 and S473 phosphorylation levels of AKT, but not with AKT expression level." (PMID 28179017, 2017). "The expression level of TMSB10 in the serum of patients with breast cancer is significantly associated with the clinical stages of breast cancer." (PMID 28179017, 2017). "We further investigated the specific mechanism underlying the overexpression of TMSB10 in breast cancer." (PMID 28179017, 2017). "Importantly, TMSB10 was significantly elevated in the serum of patients with breast cancer and positively associated with the clinical stages of breast cancer." (PMID 28179017, 2017). "Collectively, these results indicate that a potent, non-methylation-driven mechanism may underlie the deregulation of TMSB10 expression in breast cancer." (PMID 28179017, 2017). "Importantly, the expression of TMSB10 is significantly elevated in the serum of patients with breast cancer and is positively associated with clinical stages of breast cancer." (PMID 28179017, 2017). "Thus, it is generally believed that recurrent gains (amplification) are associated with high expression of TMSB10 in breast cancer." (PMID 28179017, 2017). "Our findings are consistent with most previous studies that have shown that overexpression of TMSB10 is closely related to the occurrence and development of gastric cancer, breast cancer, bladder cancer and hepatocellular carcinoma." (PMID 37275863, 2023). "A previous study reported that PI3K/Akt signal was the downstream pathway of TMSB10 and played a key role in promoting breast cancer growth and metastasis by activating the Akt/FOXO pathway." (PMID 33349268, 2020). "In breast cancer patients, increased TMSB10 expression was suggested to be correlated with short metastasis-free survival, relapse-free survival, and overall survival." (PMID 30787051, 2019). "TMSB10 expression was evaluated by immunohistochemical analysis (IHC) of 253 breast tumors and ELISA of serum from 80 patients with breast cancer." (PMID 28179017, 2017). "Collectively, these results indicate that TMSB10 promotes proliferation and tumorigenesis of breast cancer cells by accelerating the cell cycle." (PMID 28179017, 2017). "Collectively, these results demonstrate that the overexpression of TMSB10 correlates with poor prognosis and distant metastatic status in patients with breast cancer." (PMID 28179017, 2017). "So, we further measured the expression levels of TMSB10 in the serum of nine patients with breast cancer and detected TMSB10 at the approximate concentration range of 100–400 ng/ml." (PMID 28179017, 2017). "In vitro and in vivo assays were performed to assess the biological roles of TMSB10 in breast cancer." (PMID 28179017, 2017). "Cell invasion and 3D spheroid invasion assay demonstrated that upregulating TMSB10 increased the invasive ability of breast cancer cells with typical highly aggressive and invasive cell morphology, which presented a greater number of outward projections." (PMID 28179017, 2017). "In this study, we report that TMSB10 is significantly elevated in human breast cancer cells and tissues, and correlates with advanced clinicopathological features, metastasis status and poor prognosis." (PMID 28179017, 2017). "Taken together, these results suggest that TMSB10 promotes the tumorigenicity of breast cancer cells by modulating proliferation in breast cancer." (PMID 28179017, 2017). "Collectively, these results indicate that TMSB10 promotes the metastasis capability of breast cancer cells." (PMID 28179017, 2017). "Overexpression of TMSB10 promotes, while silencing of TMSB10 inhibits, proliferation, invasion and migration of breast cancer cells in vitro and in vivo." (PMID 28179017, 2017).
breast carcinoma (continued). "The mRNA expression level of TMSB10 in patients with breast cancer with gains was significantly elevated compared those without gains." (PMID 28179017, 2017). "Together, these data indicate that TMSB10 plays an important role in tumorigenesis and metastasis in patients with breast cancer." (PMID 28179017, 2017). "Our finding demonstrates that TMSB10 plays an important role in the progression and metastasis of breast cancer." (PMID 28179017, 2017). "MTT assays revealed that ectopic expression of TMSB10 significantly increased, while silencing of TMSB10 reduced, the cell numbers in breast cancer cells." (PMID 28179017, 2017). "Overexpression of TMSB10 promoted, while silencing TMSB10 inhibited, the proliferation and tumorigenesis of breast cancer cells in vitro and in vivo." (PMID 28179017, 2017). "We further examined the TMSB10 expression in the serum of a large set of patients with breast cancer and found that expression of TMSB10 in the serum was dramatically increased compared with healthy serum." (PMID 28179017, 2017). "In this study, TMSB10 was upregulated in breast cancer cell lines and tissues and high expression of TMSB10 indicated poor prognosis in patients with breast cancer." (PMID 28179017, 2017). "Our results further reveal that upregulating TMSB10 promoted the proliferation, migration and invasion of breast cancer cells by activating AKT/FOXO signaling." (PMID 28179017, 2017). "Taken together, these findings suggest that TMSB10 promotes tumor progression and metastasis in breast cancer by activating the AKT/FOXO pathway." (PMID 28179017, 2017). "In summary, our results indicate that TMSB10 plays an important role in tumorigenesis and metastasis in patients with breast cancer." (PMID 28179017, 2017). "GSEA was further performed to identify the pathways involved in TMSB10-mediated breast cancer progression." (PMID 28179017, 2017). "Univariate and multivariate analysis demonstrated that high TMSB10 expression significantly correlated with clinicopathological features, poor prognosis and distant metastases in patients with breast cancer." (PMID 28179017, 2017). "Our results further revealed that overexpression of TMSB10 promoted, while silencing of TMSB10 inhibited, proliferation, invasion and migration of breast cancer cells by activating the AKT/FOXO signaling pathway in vitro and in vivo." (PMID 28179017, 2017). "Subsequent analysis of TMSB10 expression in breast cancer datasets revealed that TMSB10 was upregulated in breast cancer tissues and breast cancer cells compared with normal breast tissue samples and epithelium cells." (PMID 28179017, 2017). "Consistently, our results revealed that TMSB10 is elevated in human breast cancer cells and tissues." (PMID 28179017, 2017). "To determine the biological roles of TMSB10 in breast cancer, we constructed TMSB10 stably expressing BT-549 and SK-BR-3 breast cancer cell lines by ectopically overexpressing TMSB10 and endogenously knocking down TMSB10 by retrovirus infection." (PMID 28179017, 2017). "Our results further reveal that TMSB10 promotes the proliferation, invasion and migration of breast cancer cells via AKT/FOXO signaling, which is antagonized by the AKT kinase inhibitor perifosine." (PMID 28179017, 2017). "Interestingly, a study of breast cancer revealed that enhanced expression of TMSB10 promoted the proliferation and migration of cancer cells by activating AKT/FOXO signaling." (PMID 36109592, 2022). "Moreover, TMSB10 expression was markedly increased in nine paired breast cancer tissue samples compared with the matched adjacent normal tissues." (PMID 28179017, 2017). "However, silencing TMSB10 displayed the opposite effect on the invasive ability of breast cancer cells." (PMID 28179017, 2017).
breast carcinoma (continued). "To investigate the effects of TMSB10 on the metastatic ability of breast cancer cells, we performed cell wound healing and migration assay and found overexpression of TMSB10 enhanced, while silencing of TMSB10 reduced, the migration ability of breast cancer cells." (PMID 28179017, 2017). "Therefore, we examined the protein levels in the supernatants of breast cancer cells using ELISA, and found TMSB10 was highly expressed in breast cancer cells compared with NMECs." (PMID 28179017, 2017). "Taken together, these results indicate that TMSB10 may be involved in human breast cancer progression." (PMID 28179017, 2017). "Furthermore, analysis using Kaplan-Meier Plotter indicates that high expression of TMSB10 predicts better response to chemotherapy in patients with breast cancer." (PMID 28179017, 2017). "High expression of TMSB10 was observed in 154/253 breast cancer tissue samples (60.9%)." (PMID 28179017, 2017). "It is worth noting that TMSB10 expression from TCGA analysis was strikingly higher in basal-like and Her2 subtypes of breast cancer, both of which presented more aggressive and malignant phenotypes characterized by high proliferation and high metastatic tendency compared with other subtypes." (PMID 28179017, 2017). "TMSB10 may hold promise as a minimally invasive serum cancer biomarker for the diagnosis of breast cancer and a potential therapeutic target which will facilitate the development of a novel therapeutic strategy against breast cancer." (PMID 28179017, 2017). "Importantly, we found that the expression level of TMSB10 in the serum of patients with breast cancer positively correlates with clinical stages of cancer in these patients." (PMID 28179017, 2017). "The purpose of this study was to determine the biological roles and clinical significance of TMSB10 in breast cancer and to identify whether TMSB10 might be used as a serum marker for the diagnosis of breast cancer." (PMID 28179017, 2017). "We further examined TMSB10 expression by immunohistochemical analysis of 253 human breast cancer tissue samples and found TMSB10 expression was primarily detected within the cytoplasm and the expression levels of TMSB10 positively correlated with clinical stages." (PMID 28179017, 2017). "Notably, Santelli and the colleagues demonstrated that overexpression of TMSB10 is a general phenomenon in human carcinogenesis, including that of breast cancer." (PMID 28179017, 2017). "Furthermore, we observed positive correlation between TMSB10 and Ki67 expression in clinical breast cancer tissue samples and tumor tissues formed by the TMSB10-overexpressing cells in vivo." (PMID 28179017, 2017). "To investigate the effects of TMSB10 on the tumorigenic activity of breast cancer cells, we performed an anchorage-independent growth assay and found overexpression of TMSB10 enhanced, while silencing of TMSB10 reduced, the anchorage-independent growth ability of breast cancer cells." (PMID 28179017, 2017). "We found TMSB10 was upregulated in breast cancer cells and tissues." (PMID 28179017, 2017). "TMSB10 is a member of the family of β-thymosins, and has been found to be overexpressed in most types of human cancers including liver cancer, gastric cancer, pancreatic cancer, cholangiocarcinoma, renal cell carcinoma, ovarian cancer, lung cancer, breast cancer, and thyroid cancer." (PMID 30787051, 2019). "Therefore, we wondered whether high expression of TMSB10 can predict chemotherapy response in breast cancer as does Ki67." (PMID 28179017, 2017). "However, the biological role and clinical significance of TMSB10 in breast cancer remains largely unknown." (PMID 28179017, 2017). "Importantly, TMSB10 can be detected in the serum of patients with breast cancer, indicating that it is clinically more convenient to measure the expression of TMSB10 than Ki67, which will help to predict the chemotherapeutic response of patients with breast cancer." (PMID 28179017, 2017).
breast carcinoma (continued). "For example, Overexpression of TMSB10 by activating the AKT/FOXO signaling pathway in vitro and in vivo could promote proliferation, invasion, and migration of breast cancer." (PMID 37275863, 2023). "The heatmap showed that the HMGA1-high cluster expressed TMSB10, CTSD and LGALS1, which are correlated with poor prognosis in breast cancer." (PMID 35611554, 2022). "Same behavior could be measured for Thymosin beta-10 (TMSB10) and this can be possibly related to the morphological change of the THP-1 cells upon treatment, as previously already reported also in breast cancer cells." (PMID 32244540, 2020). "In this study, we analyzed the methylation array dataset of breast cancer from TCGA and found that there was no obvious discrepancy between tumors and the matched adjacent normal tissue samples in the methylation levels of TMSB10." (PMID 28179017, 2017). "Through analyzing the methylation array dataset of breast cancer from TCGA, we found that in the methylation levels of TMSB10 there was no obvious discrepancy between tumor and the matched adjacent normal tissue." (PMID 28179017, 2017). "To further determine whether AKT signaling is involved in the pro-tumor role of TMSB10 in breast cancer, we applied the AKT kinase inhibitor perifosine to TMSB10-overexpressing breast cancer cells." (PMID 28179017, 2017).
bladder cancer (6 papers, 2020 to 2025). "High expression of TMSB10 was associated with the bladder cancer progression and poor prognosis of patients." (PMID 38035023, 2023). "Additionally, studies have suggested that TMSB10 may act as a potential predictive biomarker closely linked to the infiltration and development of blood vessels in lung cancer, RCC, gastric cancer, hepatocellular carcinoma, and bladder cancer." (PMID 38795225, 2024).
hepatocellular carcinoma (6 papers, 2014 to 2024). A malignant tumor that arises from hepatocytes. "CFB promote migration and proliferation of Cutaneous Squamous Cell Carcinoma47, and overexpression of TMSB10 relate with hepatocellular carcinoma and renal cell carcinoma." (PMID 33712694, 2021). "Thymosin β 10 (TMSB10) has been demonstrated to be overexpressed and function as an oncogene in most types of human cancer including hepatocellular carcinoma (HCC)." (PMID 30787051, 2019).
lung adenocarcinoma (5 papers, 2020 to 2025). A carcinoma that arises from the lung and is characterized by the presence of malignant glandular epithelial cells. "TAMs-associated TMSB10 expression was evaluated by immunohistochemistry (IHC) in 184 lung adenocarcinomas." (PMID 33349268, 2020). "To investigate the prognostic value of TAMs-associated TMSB10 in patients with lung adenocarcinoma, we had collected follow-up data and performed survival analysis." (PMID 33349268, 2020). "To identify the effect of TAMs-associated TMSB10 on the progression of lung adenocarcinoma, we conducted a xenograft model." (PMID 33349268, 2020). "In summary, these results demonstrated that TMSB10 was remarkably overexpressed in TAMs and negatively associated with the prognosis of lung adenocarcinoma, and TMSB10 knockdown dramatically repressed xenograft tumor growth in vivo." (PMID 33349268, 2020). "And high TAMs-associated TMSB10 expression was significantly correlated with poor overall and progression-free survival of lung adenocarcinoma, acting as an independent prognostic factor for lung adenocarcinoma." (PMID 33349268, 2020). "We firstly carried out the investigation on the relationship between TAMs-associated TMSB10 and the clinicopathological features of lung adenocarcinoma." (PMID 33349268, 2020). "Moreover, TMSB10 induces the immunosuppressive phenotype conversion of tumor-associated macrophages (TAMs) in lung adenocarcinoma." (PMID 36163046, 2022). "By analyzing the single-cell sequencing data and the TCGA database of lung adenocarcinoma, we suggest that the up-regulation of TMSB10 in lung adenocarcinoma and its association with poor prognosis may be due to the regulation of super-enhancers during tumor cell metastasis." (PMID 37669296, 2023). "Combined with single-cell RNA-seq and TCGA database analysis, we identified and focused on the SE-gene TMSB10 involved in EMT in lung adenocarcinoma." (PMID 37669296, 2023). "And TMSB10 mRNA is found to be overexpressed in TAMs of early lung adenocarcinoma compared with in adjacent normal lung macrophages and peripheral blood monocytes." (PMID 33349268, 2020). "In conclusion, our study found that TMSB10 may be regulated by super-enhancers in EMT of lung adenocarcinoma cells." (PMID 37669296, 2023). "This suggests that the mechanism by which TMSB10 is highly expressed in lung adenocarcinoma may also apply to other cancers." (PMID 37669296, 2023). "This suggests that TMSB10 may be regulated by super-enhancers in lung adenocarcinoma EMT and exhibit higher expression levels based on pathological status." (PMID 37669296, 2023). "Pan-cancer analysis showed that TMSB10 was abnormally expressed in most cancers, suggesting that the mechanism of action of TMSB10 on lung adenocarcinoma may be also included in other cancers." (PMID 37669296, 2023). "Therefore, in order to investigating the role of TMSB10 in TAMs of lung adenocarcinoma, we isolated the tumor-infiltrating immune cells in xenograft tumors, and found that CSF1R+ TAMs and Foxp3+ Tregs were reduced in TMSB10 knockdown group." (PMID 33349268, 2020). "Inhibition of super-enhancers regulating TMSB10 may be a new way to treat lung adenocarcinoma." (PMID 37669296, 2023). "Nevertheless, The biological role of TMSB10 in lung adenocarcinoma TAMs was still unknown." (PMID 33349268, 2020). "Taken together, our findings suggest that TAMs-associated TMSB10 promotes tumor through increasing TAMs proliferation and M2 phenotype conversion via PI3K/Akt signaling, which might be an indicator for prognosis, seems as a promising novel therapeutic target for human lung adenocarcinoma." (PMID 33349268, 2020). "Cancer-specific univariate prognostic analysis also revealed a significant correlation between TMSB10 and overall survival in multiple cancer types, including ACC, GBM, KIRC, LGG, LIHC, lung adenocarcinoma (LUAD), MESO, pancreatic adenocarcinoma (PAAD) and UVM." (PMID 36163046, 2022).
lung adenocarcinoma (continued). "However, the existence of TMSB10 in immune microenvironment may contribute to the pathogenesis of lung adenocarcinoma has not been previously explored." (PMID 33349268, 2020).